BDKRB2 (bradykinin receptor B2)
Description:
Receptor for bradykinin. It is associated with G proteins that activate a phosphatidylinositol-calcium second messenger system.
Synonyms: B2R; BKR2; BK-2; BK2; BRB2
Tractability: Small molecule: a drug acting on it is in phase 2 or 3 trials; a structure with a bound ligand is known; a high-quality ligand is known; it belongs to a druggable protein family. Antibody: UniProt places it where antibodies can reach, with high confidence; its Gene Ontology location is reachable by antibodies, with high confidence; UniProt predicts a signal peptide or a membrane-spanning region; the Human Protein Atlas places it where antibodies can reach. PROTAC: ubiquitination databases record sites on it; a small molecule that binds it is known. Other modalities: an approved drug acts on it.
Target class: Family A G protein-coupled receptor; Short peptide receptor (family A GPCR); Bradykinin receptor; Membrane receptor; Peptide receptor (family A GPCR)
Chemical probes: BRADYKININ, FASITIBANT
Safety:
Unwanted effects reported when the protein is acted on. In parentheses: how it was acted on, where the effect was seen, and who reports it.
cough (ClinPGx; Urban et al. (2012): activation, cardiovascular system)
acute allergic inflammation (activation; cardiovascular system; source: Urban et al. (2012))
angiogenesis (activation; cardiovascular system; source: Urban et al. (2012))
arrhythmia (inhibition; cardiovascular system; source: Urban et al. (2012))
arteriolar dilation/hypotension (activation; cardiovascular system; source: Urban et al. (2012))
bronchoconstriction (activation, acute dosing; respiratory, renal, central nervous system, cardiovascular; source: Lynch et al. (2017))
cardiomyopathy (inhibition; cardiovascular system; source: Urban et al. (2012))
decreased blood pressure (activation, acute dosing; respiratory, renal, central nervous system, cardiovascular; source: Lynch et al. (2017))
decreased pain (inhibition, acute dosing; respiratory, renal, central nervous system, cardiovascular; source: Lynch et al. (2017))
decreased urinary sodium excretion (inhibition, acute dosing; respiratory, renal, central nervous system, cardiovascular; source: Lynch et al. (2017))
hypertension (inhibition; cardiovascular system; source: Urban et al. (2012))
increased urinary sodium excretion (activation, acute dosing; respiratory, renal, central nervous system, cardiovascular; source: Lynch et al. (2017))
increased urine excretion (activation, acute dosing; respiratory, renal, central nervous system, cardiovascular; source: Lynch et al. (2017))
inflammation (activation, acute dosing; respiratory, renal, central nervous system, cardiovascular; source: Lynch et al. (2017))
nociception (activation; cardiovascular system; source: Urban et al. (2012))
smooth-muscle contraction (activation; cardiovascular system; source: Urban et al. (2012))
angiotensin-converting enzyme inhibitors-induced cough (source: ClinPGx)
Gene: Protein-coding gene on chromosome 14 (96,204,526 to 96,244,461, forward strand). Ensembl gene ENSG00000168398.
Subcellular location: Cell membrane
Subcellular location (Human Protein Atlas): Plasma membrane; Cytokinetic bridge; Vesicles
Pathways (Reactome):
Signal Transduction: G alpha (i) signalling events; G alpha (q) signalling events; Peptide ligand-binding receptors
Gene Ontology:
Molecular function: bradykinin receptor activity; protease binding; protein binding; protein heterodimerization activity; type 1 angiotensin receptor binding; phosphatidylinositol-4,5-bisphosphate phospholipase C activity; G protein-coupled receptor activity
Biological process: arachidonate secretion; vasodilation; blood circulation; cell surface receptor protein tyrosine kinase signaling pathway; cell surface receptor signaling pathway; G protein-coupled receptor signaling pathway; inflammatory response; positive regulation of cytosolic calcium ion concentration; regulation of vascular permeability; regulation of vasoconstriction; smooth muscle contraction; system process; vasoconstriction
Cellular component: endosome; plasma membrane; membrane
Genetic constraint (gnomAD): Loss-of-function variants: 9 observed, 6.04 expected, observed/expected ratio (o/e) 1.49, 90% interval 0.85 to 1.93. That is too few expected variants to judge how well the gene tolerates losing a copy. Missense variants: 478 observed, 490.65 expected, observed/expected ratio (o/e) 0.97, 90% interval 0.9 to 1.05. Synonymous variants: 225 observed, 200.97 expected, observed/expected ratio (o/e) 1.12, 90% interval 1 to 1.25.
Homologues: Orthologues: chimpanzee BDKRB2 (99% identical), macaque BDKRB2 (95% identical), dog BDKRB2 (81% identical), rabbit BDKRB2 (81% identical), mouse Bdkrb2 (80% identical), guinea pig BDKRB2 (79% identical), pig BDKRB2 (78% identical), rat Bdkrb2 (76% identical), tropical clawed frog bdkrb2 (48% identical), zebrafish BDKRB2 (35% identical), Caenorhabditis elegans npr-17 (17% identical). Paralogues in human: BDKRB1 (32% identical), AGTR2 (26% identical), AGTR1 (25% identical), APLNR (23% identical), GPR25 (20% identical), RXFP4 (20% identical), GPR15 (19% identical).
Diseases named in the same sentence as BDKRB2 in open-access papers:
BDKRB2 is named in the same sentence as 151 diseases in open-access papers, as found by Europe PMC text mining. Sharing a sentence is not in itself a finding about the gene and the disease. The quoted sentences say what the papers report.
angioedema (13 papers, 2018 to 2025). Swelling involving the deep dermis, subcutaneous, or submucosal tissues, representing localized edema. "Bdkrb2 is involved in the pathogenesis of hereditary angioedema, with affected individuals showing severe abdominal pain as well as swelling of the skin." (PMID 41293152, 2025). "ETV6, BDKRB2, MME, and PRKCQ were nominally associated with angioedema (p < 0.05), but none of the candidate genes was significantly associated after correction with multiple testing (p < 2.89 × 10−5)." (PMID 32080354, 2020). "In the candidate gene analysis, ETV6, BDKRB2, MME, and PRKCQ were nominally associated with angioedema (p < 0.05), but did not pass Bonferroni correction for multiple testing (p < 2.89 × 10−5)." (PMID 32080354, 2020).
glioma (13 papers, 2007 to 2025). A benign or malignant brain and spinal cord tumor that arises from glial cells (astrocytes, oligodendrocytes, ependymal cells). "In conclusion, the present study demonstrated that BDKRB2 expression was associated with more malignant glioma phenotypes and predicted much worse survival for patients." (PMID 33686021, 2021). "Gene ontology analysis demonstrated that BDKRB2 was profoundly associated with extracellular matrix organization in glioma." (PMID 33686021, 2021). "They concluded that the activation of BDKRB2 in glioma cells caused intracellular Ca2+ oscillations and subsequently enhanced glioma cell migration/invasion." (PMID 33686021, 2021). "In conclusion, BDKRB2 was associated with more aggressive phenotypes of gliomas." (PMID 33686021, 2021). "The aim of the present study was to ascertain the expression of BDKRB1 and BDKRB2 genes, as well as the level of B1R and B2R proteins in human gliomas, depending on the degree of malignancy." (PMID 38254732, 2024). "The aim of this study was to determine the expression of BDKRB1 and BDKRB2 genes and the levels of B1R and B2R proteins in human gliomas, with consideration of the degree of malignancy." (PMID 38254732, 2024). "Kaplan-Meier (KM) survival analyses were performed to examine the prognostic role of BDKRB2 in glioma." (PMID 33686021, 2021). "To elucidate the biological function of BDKRB2 in glioma, we further performed GO and GSEA analysis." (PMID 33686021, 2021). "To further validate the role of BDKRB2 in the glioma EMT process, we selected a series of EMT-related signaling pathways and biomarker, which were then analyzed to determine their interaction with BDKRB2." (PMID 33686021, 2021). "Heretofore, some researchers have investigated the potential biological functions of BDKRB2 in glioma based on in-vivo and in-vitro experimental studies." (PMID 33686021, 2021). "Bradykinin activates the bradykinin receptor B2 (B2R), leading to increases in Ca2+ and enhanced the migration of glioma cells." (PMID 25961153, 2015). "Similarly, in glioma patients with G4 grade, the BDKRB2 expression level (Me = 19,977.61 copies/μg RNA) was significantly increased (p < 0.001) compared to G2 grade (Me = 3317.50 copies/μg RNA)." (PMID 38254732, 2024). "Thus, the miR-130b-5p/BDKRB2 axis can be considered as an integral part of the pathogenesis of glioma." (PMID 36354672, 2022). "Furthermore, higher BDKRB2 expression was usually accompanied by a more aggressive and malignant phenotype in glioma, including GBM, IDH wildtype, and mesenchymal subtype." (PMID 33686021, 2021). "Moreover, higher BDKRB2 expression indicated a significantly shorter survival for patients with glioma across different WHO grades." (PMID 33686021, 2021). "According to BDKRB2 expression, pan-glioma samples were divided into two groups in each dataset." (PMID 33686021, 2021). "Understanding the molecular mechanism of BDKRB2 in glioma may provide a novel therapeutic target to overcome this fatal disease." (PMID 33686021, 2021). "BDKRB2 expression showed a positive correlation with the WHO grade of glioma." (PMID 33686021, 2021). "In glioma, only a few studies have reported that BDKRB2 was dysregulated in GBM cell lines." (PMID 33686021, 2021). "In the present study, 998 glioma patients with transcriptome data were enrolled and analyzed, aiming at investigating the clinical significance, characterization of expression profiling, and biological function of BDKRB2 in glioma." (PMID 33686021, 2021). "Finally, higher BDKRB2 indicated significantly shorter survival for glioma patients." (PMID 33686021, 2021). "In the present study, we investigated the transcriptional expression profiles of BDKRB2 in 998 glioma patients and revealed that BDKRB2 expression showed a significantly positive correlation with the WHO grade of glioma." (PMID 33686021, 2021). "However, the expression profile and prognostic value of BDKRB2 in glioma are still largely unknown." (PMID 33686021, 2021).
glioma (continued). "Furthermore, BDKRB2 was involved in the EMT process and is considered as a prognostic marker of glioma." (PMID 36354672, 2022). "BDKRB2 was increased in IDH wildtype and mesenchymal subtype of glioma." (PMID 33686021, 2021). "Besides, GO and GSEA also revealed that BDKRB2 played a vital role in the tumor-induced inflammatory response in both pan-glioma and GBM subgroup, which might be another mechanism for the oncogenic role of BDKRB2 in glioma." (PMID 33686021, 2021). "Furthermore, BDKRB2 was involved in the EMT process and could serve as an independent prognosticator in glioma." (PMID 33686021, 2021). "In addition, GSEA analyses revealed remarkable evidence that BDKRB2 expression was particularly correlated with EMT, which had been extensively confirmed to play a key role not only in glioma migration/invasion but also in glioma recurrence and therapeutic resistance." (PMID 33686021, 2021). "Moreover, most EMT biomarkers, including N-cadherin, snail, slug, vimentin, TWIST1, and TWIST2, were significantly correlated with BDKRB2, which suggested that BDKRB2 might profoundly interact with these key molecules of EMT, further confirming the involvement of BDKRB2 in glioma EMT." (PMID 33686021, 2021). "However, we could not find a systematic report about BDKRB2 expression in pan-glioma from the clinical perspective." (PMID 33686021, 2021).
Hypertension (13 papers, 2010 to 2025). The presence of chronic increased pressure in the systemic arterial system. "Allele −9 of the BDKRB2 gene is associated with arterial hypertension." (PMID 36140844, 2022). "The inhibition of GSK3A, PTP1B and BDKRB2 may be also associated with modulation of VaD risk factors, such as atherosclerosis and hypertension." (PMID 31937840, 2020). "Haplotype analysis of the candidate genes KCNJ1, NEDD4L, BDKRB2, and CACNA1C was performed to investigate the potential associations with hypertension." (PMID 39859138, 2025). "Thus, carriers of the D/D genotype of the male ACE gene (there were 37 people in this sample) and carriers of the −9 genotype of the BDKRB2 gene are recommended to prevent cardiovascular diseases, mainly arterial hypertension." (PMID 36140844, 2022).
COVID-19 (12 papers, 2020 to 2024). A disease caused by infection with severe acute respiratory syndrome coronavirus 2. "The induction of KNG1, KLK1, and BDKRB2 in primary nasal samples of SARS-CoV-2-positive study participants is evidence for an autocrine bradykinin effect via B2R that is triggered locally during COVID-19 disease." (PMID 35247068, 2022). "Altogether, these findings suggest that one ultimate pathway of SSRI antidepressant-attributed anti-COVID-19 activity is the potentiation of BDKRB2 effects shown to be inhibited in COVID-19." (PMID 36143272, 2022). "Sig1-R stimulation modulates the inflammatory response by regulating cytokine production and counterbalances COVID-19-attributed BDKRB2 inhibition by potentiating its effects on the cytosolic calcium concentration." (PMID 36143272, 2022). "Bradykinin binds to the bradykinin receptor B2 (B2R) constitutively expressed on endothelial cells and is also upregulated in COVID-19." (PMID 33375371, 2020). "Moreover, the beneficial effects obtained with acid sphingomyelinase inhibition are parallel to those expected with BDKRB2 stimulation in COVID-19." (PMID 36143272, 2022).
diabetes (10 papers, 2010 to 2023). "The main aim of this study was to evaluate the association of the BDKRB2 +9/−9 polymorphism with diabetes mellitus risk in the Brazilian general population." (PMID 23243416, 2012). "The main finding of this study was that the BDKRB2 +9/−9 polymorphism is associated with fasting glucose values and with diabetes mellitus risk in the Brazilian population." (PMID 23243416, 2012). "In this scenario, the main aim of this study was to evaluate the association of the BDKRB2 +9/−9 polymorphism with diabetes mellitus risk in the Brazilian general population." (PMID 23243416, 2012).
breast cancer (9 papers, 2011 to 2024). A primary or metastatic malignant neoplasm involving the breast. "More specifically, after silencing the CLOCK gene, the genes primarily involved in breast cancer progression included CCL5, SP100, and BDKRB2." (PMID 39587706, 2024).
Alzheimer disease (7 papers, 2015 to 2024). A progressive, neurodegenerative disease characterized by loss of function and death of nerve cells in several areas of the brain leading to loss of cognitive function such as memory and language. "Bdkrb2 was one of genes related to cerebrovascular dysfunction with the development of Alzheimer’s disease-like pathology in OXYS rats." (PMID 33731008, 2021).
colorectal cancer (7 papers, 2017 to 2023). A primary or metastatic malignant neoplasm that affects the colon or rectum. "In other types of malignancies, BDKRB2 also exhibited the biological function of promoting cell migration, invasion, and metastasis in hepatocellular carcinoma, gastric cancer, colorectal cancer, prostate cancer, head and neck squamous cell carcinoma and chondrosarcoma." (PMID 33686021, 2021). "Repression of BDKRB2, but not B1 receptor, attenuated the bradykinin-mediated invasion and migration in colorectal cancer cells, and inhibited ERK1/2 activation and IL-6 production." (PMID 28077802, 2017). "BDKRB2 as a frequently amplified molecule has been observed in a range of cancers, including cervical cancer, triple-negative breast cancer, hepatocellular carcinoma (HCC), gastric cancer, colorectal cancer, prostate cancer, bladder cancer, head and neck squamous cell carcinomas, and chondrosarcoma." (PMID 33686021, 2021).
gastric cancer (7 papers, 2020 to 2024). A primary or metastatic malignant neoplasm involving the stomach. "miR-129-1-3p functions as a tumor inhibitor via targeting BDKRB2 in gastric cancer (Wang, Luo & Guo, 2014)." (PMID 34123589, 2021). "BDKRB2, an angiogenesis-related gene, demonstrated as a direct IRX1 target gene and was reported to be involved in gastric cancer progression." (PMID 34938313, 2021). "In gastric cancer, IRX1 acts a tumor suppressor through downregulation of BDKRB2, FGF7, and HIST2H2BE expression and inhibiting angiogenesis and cell proliferation." (PMID 33256112, 2020). "Previous studies have shown that miR-129-1-3p may inhibit the migration of the human gastric cancer cell line BGC-823 by targeting and regulating bradykinin receptor B2 (BDKRB2), thereby inhibiting the metastasis of gastric cancer." (PMID 38818039, 2024).
hereditary angioedema (6 papers, 2017 to 2025). Hereditary angioedema (HAE) is a genetic disease characterized by the occurrence of transitory and recurrent subcutaneous and/or submucosal edemas resulting in swelling and/or abdominal pain. "HOE 140, a selective Bdkrb2 antagonist, is clinically used as a pharmaceutical agent for treatment of acute attacks of hereditary angioedema, as it can effectively reduce pain and swelling." (PMID 41293152, 2025). "Considering non-genome based research, icabitant (Firazyr) is a bradykinin receptor B2 antagonist, used to treat acute attacks of hereditary angioedema." (PMID 28481922, 2017).
endothelial dysfunction (5 papers, 2010 to 2022). In vascular diseases, endothelial dysfunction is a systemic pathological state of the endothelium (the inner lining of blood vessels) and can be broadly defined as an imbalance between vasodilating and vasoconstricting substances produced by (or acting on) the endothelium. "Because BDKRB2 enhanced the endothelial dysfunction of Tg-B2++ApoE–/– mice, we asked whether inhibition of ACE-dependent angiotensin II generation in Tg-B2++ApoE–/– mice could retard the BDKRB2-enhanced atherosclerosis progression." (PMID 30847343, 2019).
glioblastoma (5 papers, 2012 to 2024). The most malignant astrocytic tumor (WHO grade IV). "Levels of BDKRB1 and BDKRB2 were detected in human U87 MG glioblastoma cells (top two panels, lane 1)." (PMID 32182968, 2020).
Stroke (5 papers, 2008 to 2022). Sudden impairment of blood flow to a part of the brain due to occlusion or rupture of an artery to the brain. "Recently these results have been consistently contested, leading to the conclusion that the deficiency of bradykinin receptor B2 is not detrimental in experimental stroke, and may be beneficial in other pathological conditions." (PMID 18986535, 2008).
brain tumor (4 papers, 2007 to 2020). "Bdkrb2 agonist (lobradimil) has either been used or currently in clinical trials for treating brain tumors and HIV-infected individuals with cryptococcal meningitis (ClinicalTrials.gov: NCT00005602, NCT00019422, NCT00001502, and NCT00002316)." (PMID 30405320, 2018).
colitis (4 papers, 2015 to 2025). Inflammation of the colon. "In the kidney, colitis induced localization of tubular bradykinin receptor B2 to the nuclear envelope and increased kininogen 2 transcription." (PMID 40018982, 2025).
heart failure (4 papers, 2008 to 2025). Inability of the heart to pump blood at an adequate rate to meet tissue metabolic requirements. "rs8012552 of BDKRB2 was significantly linked with total protein (p-value = 0.035), Na level (p-value = 0.033), number of years of HTN (p-value = 0.046), and heart failure (p-value = 0.019)." (PMID 39859138, 2025). "rs1799722 of BDKRB2 was significantly associated with HbA1c levels (p-value = 0.035), sodium (Na) level (p-value = 0.033), number of years with HTN (p-value = 0.046), ejection fraction (EF) (p-value = 0.03), and heart failure (p-value = 0.019)." (PMID 39859138, 2025). "This could be explained by the fact that the abnormal structure of BDKRB2 gene is related to heart failures." (PMID 34236536, 2021).
prostate carcinoma (4 papers, 2020 to 2024). A carcinoma that arises from epithelial cells of the prostate gland. "The expression of Bdkrb2 was also detected in human endometrial and prostate cancers." (PMID 33731008, 2021).